SERPINB2 (serpin family B member 2)
Diseases named in the same sentence as SERPINB2 in open-access papers (continued):
Sharing a sentence is not in itself a finding about the gene and the disease.
prostate carcinoma (10 papers, 2002 to 2025). A carcinoma that arises from epithelial cells of the prostate gland. "The genetic screening of the donor who had colon cancer, prostate cancer, and succumbed to heart failure identified three genes linked to the latter - ARMT1, CPXM2, and SERPINB2 - along with a plethora of genes associated with cancer, including those of colorectal and prostate." (PMID 41234971, 2025). "The differences between PC1 and PC2 cells can explain the differences in therapy response and SERPINB2 could be studied in the future s as one candidate marker for TP resistance in canine prostate carcinoma." (PMID 33324695, 2020). "It will be attractive to verify if carcinogenesis of prostate cancer cells were due to such coordinated epigenetic switches of these SERPINB genes, since some of them are known tumor suppressor genes, such as SERPINB2 and SERPINB5, and can contribute to decreased tumor growth and metastasis." (PMID 19262738, 2009).
ovarian carcinoma (8 papers, 2004 to 2025). A malignant neoplasm originating from the surface ovarian epithelium. "The role of SERPINB2 has been implicated in several cancer types, such as bladder, endometrial, colorectal, and ovarian cancers." (PMID 39744516, 2025). "High concentrations of SERPINB2 in a neoplastic tissue are associated with good prognosis in patients with breast, pancreatic, and ovarian cancers." (PMID 31590218, 2019). "The upregulated genes encode for proteins associated with ovarian cancer metastasis [SERPINB2/PAI2], metabolic activities [IDI1, PMM2] and gene expression/transcription [PCGF6, ZNF267]." (PMID 22022533, 2011). "In HIO-80 cells, there was significant upregulation of genes encoding for proteins associated with ovarian cancer metastasis [SERPINB2/PAI2], metabolic activities [IDI1, PMM2] and gene expression/transcription [PCGF6, ZNF267]." (PMID 22022533, 2011). "SERPINB2, also named Plasminogen Activator Inhibitor, Type II (PAI-2) is upregulated by numerous inflammatory conditions; in cancer disease its expression is often an indicator of positive prognosis as described in ovarian cancer." (PMID 27259239, 2016).
Sepsis (8 papers, 2015 to 2025). Sepsis is defined as life-threatening organ dysfunction caused by a dysregulated host response to infection. "The presence of SERPINB2 in plasma is associated with sepsis outcomes." (PMID 41285832, 2025). "In addition, CD59, SERPINB2, CFD, and P2RX1 can be potential biomarkers for sepsis diagnosis." (PMID 41285832, 2025).
breast tumor (7 papers, 1994 to 2024). "SerpinB2-deficient mouse embryonic fibroblasts exhibit increased pancreatic tumor growth and local invasion with reduced collagen deposition, whereas fibroblasts overexpressing SerpinB2 reduce human breast tumor cell apoptosis." (PMID 35768767, 2022). "We also explored the clinical significance of SerpinB2 protein status through analysis of primary breast tumor samples and The Cancer Genome Atlas (TCGA) data." (PMID 28427146, 2017). "Overall, the inhibitory actions triggered by E4 through the GPER/ERK/SERPINB2 pathway in TNBC cells may provide novel insights concerning the biological effects of E4 in the aggressive breast tumor subtype namely TNBC." (PMID 38741146, 2024).
hypercoagulability (7 papers, 2010 to 2023). "Moreover, from a biological point of view, SERPINB2 regulates the plasminogen activator-2 inhibitor pathway, which is responsible for a fibrinolytic mechanism that is less associated with APS-related hypercoagulability." (PMID 37035297, 2023).
Hypertension (6 papers, 2012 to 2018). The presence of chronic increased pressure in the systemic arterial system. "The common area between the hypertension only- and hypercholesterolemia plus sham groups showed up-regulated focus genes related to UBC, APP, SERPINB2, TNF and HNF4A, and down-regulated focus genes related to UBC." (PMID 23874591, 2013). "The network with the second largest number of up-regulated focus genes also had many similarities with the hypertension only group, with P38 MAPK, ERK 1/2, NFkB, SERPINB2 and Akt being central players, together with focus genes related to interferon alpha and VEGF." (PMID 23874591, 2013).
coronary artery disease (5 papers, 2007 to 2023). "The role of SerpinB2 polymorphisms may also warrant investigation as they have been linked with both lupus and coronary heart disease, conditions also modified by HIV infection." (PMID 23460840, 2013).
leukemia (5 papers, 2015 to 2023). A malignant (clonal) hematologic disorder, involving hematopoietic stem cells and characterized by the presence of primitive or atypical myeloid or lymphoid cells in the bone marrow and the blood. "Furthermore, SERPINB2 has been identified as one of the synergistically dysregulated genes that stimulate leukemia stem cell proliferation and survival." (PMID 29925837, 2018). "The expression of ZNF198-FGFR1 is related to specific PAI-2 (plasminogen activator inhibitor-2/SERPINB2)-mediated anti-apoptosis, which is possibly one of the reasons for the high malignancy of leukemia cells." (PMID 36408177, 2022).
cholangiocarcinoma (4 papers, 2018 to 2022). A carcinoma that arises from the intrahepatic biliary tree (intrahepatic cholangiocarcinoma) or from the junction, or adjacent to the junction, of the right and left hepatic ducts (hilar cholangiocarcinoma). "On the contrary, SERPINB2 expression induced cancer cell migration and was associated with a poor survival rate in cholangiocarcinoma patients." (PMID 36497110, 2022).
colorectal cancer (4 papers, 1997 to 2019). A primary or metastatic malignant neoplasm that affects the colon or rectum. "In recurrent colorectal cancers, the levels of positive regulators of SERPINB2, such as TNF (Z-score = 5.021, p-value = 0.301), JUNB (Z-score = 1.533, p-value = 0.00515) and ERK (Z-score = 3.763, p-value = 0.171), were also increased." (PMID 30965654, 2019).
Depression (4 papers, 2015 to 2022). "No studies have reported a direct association of S100A12, TIGIT, SERPINB2, GRB10, and LHFPL2 with depression." (PMID 36325528, 2022). "S100A12, TIGIT, SERPINB2, GRB10, and LHFPL2 identified as potential diagnostic biomarkers in peripheral blood of patients with depression using three machine learning algorithms." (PMID 36325528, 2022). "Subsequently, S100A12, TIGIT, SERPINB2, GRB10, and LHFPL2 in peripheral blood were identified as Potential diagnostic biomarkers in peripheral blood for depression by SVM–REF, Random forest, and LASSO algorithms." (PMID 36325528, 2022). "The genes S100A12, TIGIT, SERPINB2, GRB10, and LHFPL2 in peripheral serum are viable diagnostic biomarkers for depression." (PMID 36325528, 2022). "ROC analysis based on both GSE98793 and GSE76826 datasets suggested that S100A12, TIGIT, SERPINB2, GRB10, and LHFPL2 in the peripheral serum have the potential to act as diagnostic biomarkers for depression." (PMID 36325528, 2022). "Based on the results of the ROC (validation set AUC value > 0.7) analysis in the current study, S100A12, TIGIT, SERPINB2, GRB10, and LHFPL2 may possess potential as diagnostic biomarkers of depression." (PMID 36325528, 2022). "Subsequently, the genes S100A12, SERPINB2, TIGIT, GRB10, and LHFPL2 in peripheral serum were identified as depression biomarkers by using machine learning algorithms." (PMID 36325528, 2022). "Among them, the relevance scores of S100A12, TIGIT, SERPINB2, GRB10, and LHFPL2 with depression were 4.356, 4.232, 3.064, 1.516, and 0.698, respectively." (PMID 36325528, 2022). "The expression level of 100A12, SERPINB2, GRB10, and LHFPL2 was higher in the depression group, whereas TIGIT showed a high expression profile in the normal control group." (PMID 36325528, 2022). "We further investigated the role of S100A12, TIGIT, SERPINB2, GRB10, and LHFPL2 in depression and observed their expression profiles in patients." (PMID 36325528, 2022). "Finally, the results from the three algorithms were combined, yielding S100A12, TIGIT, SERPINB2, GRB10, and LHFPL2 in peripheral blood as depression-related potential biomarkers." (PMID 36325528, 2022). "Initially, the correlation analysis showed that TIGIT had a significantly negative correlation with the level of SERPINB2 and GRB10 expression in patients with depression." (PMID 36325528, 2022).
lupus (4 papers, 2013 to 2024). "More specifically, SERPINB2 has been identified as the most upregulated gene in peripheral blood monocytes of patients with inflammatory bowel disease and in monocytes of patients with systemic lupus erythematosus." (PMID 39456691, 2024).
psoriasis (4 papers, 2022 to 2024). An autoimmune condition characterized by red, well-delineated plaques with silvery scales that are usually on the extensor surfaces and scalp. "Thus, miR-146a/b and SERPINB2 coordinately act in the hindrance of psoriasis-associated inflammation." (PMID 36008966, 2022). "Some serpins, including SerpinA12, SerpinB2/3//7 play multiple roles in skin barrier function and pathogenesis of psoriasis." (PMID 39737188, 2024). "Some Serpins, including SerpinA12, SerpinB2/B3/B7, play multiple roles in skin barrier function and pathogenesis of psoriasis." (PMID 39737188, 2024). "The expression levels of SerpinB2 in the psoriasis-involved skin are positively correlated with the severity of psoriasis." (PMID 39737188, 2024). "MiR-146a/b collaborates with serpinB2 in keratinocytes to regulate inflammation in psoriasis." (PMID 39737188, 2024). "Additionally, it has been reported that SERPINB2 plays a role in regulating inflammatory responses in psoriasis." (PMID 39456691, 2024). "Like SerpinB2, B3, SerpinB1 is elevated in lesional skin of psoriasis patients." (PMID 39737188, 2024). "In addition, knockout of CARMA3 led to downregulation of serpin family B member 2 (SERPINB2) at both the mRNA and protein levels, which is positively related to psoriasis severity." (PMID 36618379, 2022).
Stroke (4 papers, 2019 to 2023). Sudden impairment of blood flow to a part of the brain due to occlusion or rupture of an artery to the brain. "SerpinB2 has been studied as a potential treatment in a mouse stroke model and proven to be effective in reducing brain damage." (PMID 36309755, 2022).
allergic asthma (3 papers, 2020 to 2025). A asthma with a basis in a pathological type I hypersensitivity reaction. "Top “Th2-high” genes with marker potential in allergic asthma are POSTN and SERPINB2." (PMID 32157178, 2020).
allergic rhinitis (3 papers, 2022 to 2025). Inflammation of the nasal mucous membranes caused by an IgE-mediated response to external allergens. "It’s necessary to evaluate the role of SerpinB2 in different type of allergic rhinitis when more types of AR patients are available." (PMID 41142810, 2025). "The last allergic rhinitis study showed that human mesenchymal stem cells (HMSC)-EVs co-cultured with CD4+ T cells inhibited the Th2 differentiation by regulating the miR-146a-5p/SERPINB2 pathway." (PMID 38674077, 2024).
bladder cancer (3 papers, 2017 to 2022). "SERPINB2 was also reported as a regulator or biomarker for predicting the malignant progression of colorectal and bladder cancer." (PMID 35433683, 2022).
nasal polyps (3 papers, 2021 to 2026). "In a controlled experiment, SERPINB2 was found to be increased in eosinophilic chronic rhinosinusitis with nasal polyps (CRSwNP) nasal polyp epithelial cells and to promote T2 inflammation through STAT6 signaling, which could be considered a novel therapeutic target for CRSwNP." (PMID 41511918, 2026). "In our previous study, we found that SerpinB2 induced by IL-13 contributes to the expression of 15-lipoxygenase-1 (15LO1) and its downstream markers, such as CCL26 and iNOS in nasal polyp epithelial cells." (PMID 41142810, 2025). "The abnormal expression of coagulation factors involved in tissue remodeling of nasal polyps was also significantly corrected using GC, with a significant increase in PLG and a decrease in F13A, SERPINE1, and SERPINB2." (PMID 35095530, 2021).
squamous cell carcinoma (3 papers, 2015 to 2025). A carcinoma arising from squamous epithelial cells. "In contrast, high SerpinB2 was associated with reduced LCSS in stage I squamous cell carcinomas (p = 0.022)." (PMID 29207598, 2017). "The median SERPINB2 RNA level in lung tumor tissues was also significantly higher than that in normal tissues (4.625 versus 3.950, P = 0.0053) and this difference was predominant in squamous cell carcinoma." (PMID 26338969, 2015). "Tumor epithelial clusters expressed canonical squamous carcinoma markers such as CLDN1, LAMB3, TP63, CDKN2A, EPCAM, and SERPINB2, validating their malignant identity, while stromal and immune subsets displayed expected transcriptional programs." (PMID 41510303, 2025). "In stage I squamous cell carcinomas, a multivariate model where variables with p<0.10 in univariate survival analysis (BVI and SerpinB2) were included, showed that high SerpinB2 was an independent prognostic factor for reduced LCSS (HR 3.5 (95 % CI 1.03-11.74), p = 0.044)." (PMID 29207598, 2017).
venous thromboembolism (3 papers, 2012 to 2025). Occlusion of the lumen of a vein by a thrombus that has migrated from a distal site via the blood stream. "We chose to quantify ANXA3, TNFAIP6, TXK, BACH2, and SERPINB2 mRNA expression in t-PAPS based on the results of a meta-analysis using a bioinformatics panel to explore the differences and similarities between venous thromboembolism (VTE) and cardiovascular disease." (PMID 37035297, 2023).
viral infection (3 papers, 2019 to 2023). "Post PCV2 infection, we identified 199 differentially expressed lncRNAs, which appear to modify genes associated with viral infection, such as SOD2, TNFAIP3, ARG1, SERPINB2, VLDLR, HSPA5, and LCN2." (PMID 30863688, 2019).
amoebiasis (2 papers, 2016 to 2022). "CYP1A1 and SERPINB2 displayed high expression levels along with T. gondii infection, and these two genes are involved in chemical carcinogenesis and amoebiasis, respectively." (PMID 27242740, 2016).
autoimmune disease (2 papers, 2024 to 2025). A disorder resulting from loss of function or tissue destruction of an organ or multiple organs, arising from humoral or cellular immune responses of the individual to their own tissue constituents. "SERPINB2 has been implicated in many exogenous inflammatory and autoimmune diseases; however, to date, there is relatively little research on its role in liver disease." (PMID 39936105, 2025). "Vtcn1, also known as B7–H4, is similar to Serpinb2, it is not directly related to pain; however, its importance in immune response has made it a therapeutic target for the treatment of tumors, inflammation, autoimmune diseases, and organ transplantation." (PMID 38813203, 2024).
brain ischemia (2 papers, 2013 to 2019). Diminished or absent blood supply to the brain caused by obstruction (thrombosis or embolism) of an artery resulting in neurologic damage. "Increased SERPINB2 expression is found in the AD brain, and after brain ischemia or trauma, particularly in the basement membrane and endothelial cells of vessels adjacent to the lesion." (PMID 23874591, 2013).
cervical cancer (2 papers, 2014 to 2026). A primary or metastatic malignant neoplasm involving the cervix. "Whether tumor-cell SerpinB2 is mutated or functionally inactive is also unclear, although for the cervical cancer cell line, CaSki, SerpinB2 was found to be unmutated and active with respect to uPA inhibition." (PMID 24644264, 2014). "Cluster 8 was the most enriched for KRT78 and SERPINB2, both of which have been shown to exhibit increased expression in HPV‐associated cervical cancers." (PMID 41362277, 2026).
diabetic kidney disease (2 papers, 2023 to 2024). Progressive kidney disorder caused by vascular damage to the glomerular capillaries, in patients with diabetes mellitus. "Interestingly, reduced levels of SerpinB2 have been associated with the delayed development of diabetic nephropathy." (PMID 36769128, 2023).
fibrosarcoma (2 papers, 2014 to 2015). A malignant mesenchymal fibroblastic neoplasm affecting the soft tissue and bone. "Following subcutaneous injection of these cells into nude mice, fibrosarcoma were formed from SLC30A1- or SERPINB2-expressing cells." (PMID 26338969, 2015).
gastric adenocarcinoma (2 papers, 2017 to 2018). "We undertook a systematic review evaluating expression of uPA, urokinase plasminogen activator receptor (uPAR), plasminogen activator inhibitor-1 (PAI-1/SerpinE1) and plasminogen activator inhibitor-2 (PAI-2/SerpinB2) on primary oesophageal, gastro-oesophageal junction, and gastric adenocarcinomas." (PMID 28416743, 2017).
head and neck cancer (2 papers, 2021 to 2023). A primary or metastatic malignant neoplasm affecting the head and neck. "In addition, decreased SERPINB2 expression in head and neck cancer cell lines has been associated with acquired cisplatin resistance." (PMID 36982651, 2023). "In line with this, overexpression of SERPINB2 in nasopharyngeal carcinoma cells also decreased invasiveness suggesting a tumor suppressive role in human head and neck cancers." (PMID 34116687, 2021).
hemorrhage (2 papers, 2022). Loss of blood from the vascular compartment to the exterior or into nonvascular body space as a result of rupture or severance of the blood vessels. "Meanwhile, the transcription of several coagulation-related genes, including THBD and SERPINB2, is substantially upregulated by VP35-dependent CREB1 activation, which may contribute to EBOV-related hemorrhage." (PMID 35474062, 2022).
liver cancer (2 papers, 2019 to 2022). An epithelial or non-epithelial malignant neoplasm that arises from the liver. "GSEA revealed a strong relationship between the significantly enhanced expression of SERPINB2 and metastatic progression or recurrence in multiple cancer types, including breast, colorectal and liver cancers." (PMID 30965654, 2019). "SERPINB2 might act as a regulator or biomarker for predicting metastatic progression in breast and liver cancers." (PMID 36497110, 2022). "Finally, in invasive liver cancers, the levels of positive regulators of SERPINB2, such as TAL1 (Z-score = 3.982, p-value = 0.237), FOSL1 (Z-score = 1.483, p-value = 0.0311) and FOS (Z-score = 3.214, p-value = 0.0347), were increased." (PMID 30965654, 2019). "Furthermore, to confirm whether SERPINB2 can mediate the tumorigenic potential of various types of CSCs, we knocked down SERPINB2 expression using a specific shRNA in breast, colorectal and liver cancer cells." (PMID 30965654, 2019). "Consistent with the IPA results, our immunocytochemical analysis showed that SERPINB2 expression was markedly increased in tumor tissues compared to non-tumor tissues in breast, colorectal and liver cancer patients." (PMID 30965654, 2019). "Additionally, to investigate the correlations between SERPINB2 and CSC populations in various cancer patients, we analyzed the co-expression of SERPINB2 in CD44-, CD133- or ALDH-positive tissue samples from breast, colorectal and liver cancer patients, respectively." (PMID 30965654, 2019).
lung adenocarcinoma (2 papers, 2015 to 2017). A carcinoma that arises from the lung and is characterized by the presence of malignant glandular epithelial cells. "Our main finding is that low SerpinB2 expression in primary tumors is independently associated with reduced cancer specific survival in lung adenocarcinomas." (PMID 29207598, 2017). "The authors used mRNA levels of SerpinB2 and Neuroserpin in survival analyses of 106 primary lung adenocarcinomas with brain metastasis as end-point." (PMID 29207598, 2017). "In summary, low expression of SerpinB2 in lung adenocarcinomas was an independent prognostic factor." (PMID 29207598, 2017). "Thus, low expression of SerpinB2 could be a biomarker for prognosis in lung adenocarcinomas." (PMID 29207598, 2017).